GATA2 (GATA binding protein 2)
Diseases named in the same sentence as GATA2 in open-access papers (continued):
Sharing a sentence is not in itself a finding about the gene and the disease.
acute myeloid leukemia (continued). "Disturbance of mRNA expression of erythroid transcription factors, such as EKLF, GATA1 or GATA2, has been shown in patients with acute myeloid leukemia (AML), but no direct link to the mutations responsible for leukemogenesis has been demonstrated." (PMID 22676581, 2012). "GATA2 mutations are associated with a heightened risk of myelodysplastic syndromes (MDS) and acute myeloid leukemia (AML)." (PMID 41154393, 2025). "GATA2 mutations have been observed in CNKD patients with haematopoietic malignancies, especially myelodysplastic syndrome, and acute myeloid leukemia (MDS-AML)." (PMID 31379882, 2019). "Of note, mutations in several of the genes that confer leukemia predisposition (e.g., CEBPA, ETV6, GATA2, NF1, RUNX1, PTPN11, CBL, and RAS) are also frequently found in sporadic acute myeloid leukemia (AML) or myelodysplastic syndrome (MDS)." (PMID 29326930, 2017). "Recently it has been reported that reduction of GATA2 by shRNA or the inhibitor K7174 sensitizes KG1a acute myeloid leukemia cells to chemotherapy, suggesting that suppression of GATA2 expression or inhibition of its transcriptional activity may have potential as an ancillary therapy in AML." (PMID 29029492, 2017). "In OSCC, overexpression of miR-626 targets and inhibits RASSF4 translation, whereas in acute myeloid leukemia (AML), GATA-binding protein 2 (GATA2) significantly reduces RASSF4 expression levels." (PMID 41007433, 2025). "GATA2 deficiency is autosomal dominant in nature and is associated with several abnormalities, such as cytopenias, recurrent infections, immunodeficiency, and myelodysplastic syndrome (MDS), with a high risk of transformation to acute myeloid leukemia (AML)." (PMID 40981111, 2025). "In cases of acute myeloid leukemia (AML), the relocation of the distal GATA2 enhancer due to translocations or inversions of chromosome 3 can result in the abnormal activation of the EVI1 oncogene through the translocation-derived super enhancer." (PMID 39838405, 2025). "Furthermore, while GATA2-deficient patients have profound monocytopaenia, immunodeficiency and an increased risk of myelodysplasia and acute myeloid leukaemia, none of the patients with WILD in this series had either abnormal monocyte counts or developed myelodysplasia." (PMID 34916230, 2023). "Heterozygous GATA-2 germline mutations are associated with overlapping clinical manifestations termed GATA-2 deficiency, characterized by immunodeficiency and predisposition to myelodysplastic syndrome (MDS) and acute myeloid leukemia (AML)." (PMID 24782121, 2014). "A case in point is the 3q rearrangements, which repositions a distal GATA2 enhancer to ectopically activate EVI1, and simultaneously confer GATA2 functional haploinsufficiency, thereby contributing to sporadic occurrence of familial acute myeloid leukemia." (PMID 41009620, 2025). "Another confounding factor in these patients is that that GATA2 and MCM4—the two main genes involved in the origin of CNKD—could be relevant in carcinogenesis, including GATA2 mutations identified in families with predisposition to myelodysplastic syndrome and acute myeloid leukemia (MDS-AML)." (PMID 35203609, 2022). "Also, the expression of GATA2 is significantly higher in AML compared to normal bone marrow, and recently Maaike Luesink and his colleagues found that high GATA2 expression was a poor prognostic marker in acute myeloid leukemia as well as other transcription factors EVI,WT1." (PMID 28114350, 2017). "GATA2, CEBPA and CSF1R have been reported in MDS and acute myeloid leukemia (AML)." (PMID 27959900, 2016). "Loss-of-function GATA2 mutations have been reported in patients with familial myelodysplastic syndrome and acute myeloid leukemia (MDS/AML), but GATA2 mutations have not been reported in neuroblastoma." (PMID 24147068, 2013).
acute myeloid leukemia (continued). "In this article, we report five patients with different hematological and immunological manifestations of GATA2 deficiency ranging from immunodeficiency and refractory cytopenia of childhood without chromosomal aberrations to relapsed MDS-related acute myeloid leukemia." (PMID 38993648, 2024). "Patients with a monoallelic germline mutation in GATA2 present with hematologic complications early in life, accompanied by a significantly increased risk of developing myelodysplastic syndrome (MDS), which may progress to acute myeloid leukemia (AML) via a precarious malignant transformation." (PMID 38067298, 2023). "GATA2 dysfunction may present in the first two decades with lymphedema, deafness and myelodysplasia (Emberger syndrome), or acute myeloid leukemia without preceding immunodeficiency." (PMID 26812071, 2016). "GATA2, 3-fold overexpressed after ESR2 knockdown in HEC-1A cells, is a transcription factor, which has been reported to be overexpressed in non-familial EVI1-positive acute myeloid leukemia as well as in prostate cancer." (PMID 31357971, 2019). "Mono-Allelic germline disruptions of the transcription factor GATA2 result in a propensity for developing myelodysplastic syndrome (MDS) and acute myeloid leukemia (AML)." (PMID 34633564, 2021).
leukemia (78 papers, 2010 to 2025). A malignant (clonal) hematologic disorder, involving hematopoietic stem cells and characterized by the presence of primitive or atypical myeloid or lymphoid cells in the bone marrow and the blood. "Although this test primarily examines somatic changes in leukemia cells, it also identifies changes in the germline, leading to an expected improvement in the diagnosis of GATA2 deficiency." (PMID 40821825, 2025). "In contrast, Patient 1 was diagnosed with GATA2 deficiency >6 months after initiating leukemia treatment, as the atypical initial presentation with Crohn’s disease delayed recognition." (PMID 40821825, 2025). "The onset of GATA2 deficiency ranges from early childhood to late adulthood, presenting clinically with a spectrum from asymptomatic to life‐threatening infections, leukemia, and respiratory failure." (PMID 39981594, 2025). "The diagnoses of the patients included primary immunodeficiency diseases (DOCK8: n=4, STAT3: n=1, GATA2 mutations: n=11), lymphoma (n=3), leukemia (n=5), and sickle cell disease (n=5)." (PMID 38756303, 2024). "The pathogenic dysfunction of GATA2 gene is increasingly gaining significance in clinical management of leukemia." (PMID 39126219, 2024). "Studies have indicated a higher frequency of leukemia in patients with GATA2 missense variants and an increased risk of lymphedema in those with null variants." (PMID 38137719, 2023). "Altogether, our data suggest that loss of TET2 in CebpaDM AML causes a moderate decrease in Gata2 expression, which in turn increases the competitive fitness of the leukemia." (PMID 37794021, 2023). "For example, one cell line (KCL019) carried a variant in GATA2, a transcription factor important for immune cell development and associated with immunodeficiency and leukemia when disrupted." (PMID 35176222, 2022). "The heterozygous knockout of GATA2+/− in mice caused the inhibition of abnormal myeloid-progenitor-cell proliferation and differentiation and leukemia inhibition in Cbfb-MYH11 transgenic mice." (PMID 35269883, 2022). "GATA2 mutations are responsible for Emberger syndrome, carriers of this mutation are predisposed to leukaemia and lymphoedema, this is due to the crucial role of GATA2 in the differentiation of LECs specifically in the lymphovenous vales." (PMID 34795596, 2021). "Study showed that GATA2 activity affected the mutational dynamics of leukemia in Cbfb-MYH11 knockin mice." (PMID 34485141, 2021). "Although GATA2 is established as one of the key regulators of embryonic and adult hematopoiesis, the mechanisms behind the leukemia predisposition in GATA2 haploinsufficiencies is ambiguous." (PMID 34713225, 2020). "A previous study has indicated that GATA2 mutation is associated with a greater risk of cumulative incidence of relapse (CIR) or shorter leukemia-free survival (LFS) in newly diagnosed AML patients treated with a combination of decitabine, cytarabine, aclarubicin, and G-CSF (DCAG)." (PMID 40002181, 2025). "Further studies revealed that CEBPA mutations enhance its ability to bind and regulate the GATA2 enhancer, working in conjunction with TET2 mutations to rebalance GATA2 expression levels, thereby conferring greater competitiveness and aggressiveness to leukemia cells." (PMID 40032852, 2025). "This was also evident by a mouse model that showed biallelic C\ebpα led to myeloid leukemia development, and the addition of Gata2 mutation to the latter promoted leukemia progression, with 40% of triple transgenic mice developing leukemia with both erythroid and myeloid features." (PMID 38892446, 2024). "The discovery of GATA2 mutant in AML susceptibility family provides a new method to explore the mechanism of GATA2 inducing leukemia, and may clarify its role in maintaining “stem”." (PMID 36824144, 2023).
leukemia (continued). "GATA2 deficiency is an autosomal dominant, pleiotropic disease with clinical manifestations that include bone marrow failure, monocyte and B cell deficiency, leukemia, pulmonary alveolar proteinosis and lymphedema." (PMID 36726998, 2023). "Interestingly, a study on the effect of hypomorphic Gata2 variants in mice showed that reduction of GATA2 expression to ~20% induced development of chronic myelomonocytic leukemia‐like leukemia." (PMID 34387894, 2021). "This further suggests a dose dependent effect of Gata2a in hematopoietic cells may drive the leukemic phenotype, or the acquisition of second hit mutations that drive the formation of leukemia’s in GATA2 deficiency." (PMID 34589480, 2021). "In addition, we identify a mechanism whereby transcriptional and epigenetic changes, induced by Cebpa and Gata2 mutation, respectively, synergize to define the lineage identity of the resulting leukemia." (PMID 32330454, 2020). "Regulation of GATA2 expression is crucial in HSCs and in leukemia predisposition." (PMID 34713225, 2020). "The knowledge that GATA2 mutation is a constitutive risk factor for MDS/AML begs an important question of whether acquired GATA2 mutation is among the key leukaemia-initiating events in sporadic MDS/AML." (PMID 25707267, 2015). "Caused by heterozygous loss-of-function GATA2 gene variants, haploinsufficiency of GATA2, also known as GATA2 deficiency, leads to a wide spectrum of clinical manifestations including mycobacterial infections, viral infections, bone marrow failure, leukemia and lymphedema." (PMID 37680631, 2023). "This raises the question of how, and in which cell type, synergy between CEBPA and GATA2 mutations is achieved, and in particular whether the bilineage leukemia phenotype is maintained by a single bipotent, or by two distinct lineage-restricted, leukemia-propagating cell populations." (PMID 32330454, 2020). "Furthermore, in GATA2 haploinsufficiency patients, additional mutations in other genes could be the driver of leukemia which brings challenges to treat these patients by only correcting the mutant GATA2 allele." (PMID 34713225, 2020). "In K562, the transcription factor E2F6, which might function as a repressor, is enriched in K562 single enhancers, while transcription factors STAT5, TAL1 and GATA2, which are all associated with growing culture and differentiation of leukemia cell, are significantly enriched in redundant enhancers." (PMID 30563465, 2018). "In contrast, GATA2 functions as an anti-inflammatory effector in hematopoietic progenitor cells, leukemia cells, and prostate cancer." (PMID 40516868, 2025). "In sharp contrast, stem cell gene, Cd34; lineage gene, Gata2; and leukemia stem cell regulator, Ikzf2; as well as Tnfaip3, Pvr (Cd155), and Nectin2 (Cd112), were upregulated in Vav-cre Tet2fl/flTp53fl/fl GMPs." (PMID 40111422, 2025). "RUNX1 activates the AP-1/GATA2 axis in the bone marrow microenvironment, thereby leading to the aberrant proliferation of leukemia stem cells and the promotion of their immune escape." (PMID 39422621, 2024). "Altogether, our work proposes that CEBPA-mutant AMLs acquire additional lesions in genes such as GATA2 and TET2 to reestablish balanced GATA2 levels that permit leukemia development and progression." (PMID 37794021, 2023). "Strikingly, we found that while moderate reduction of Gata2 expression increased competitiveness in CebpaDM AML both in vivo and in vitro, leukemia cells remain critically dependent on residual GATA2 function." (PMID 37794021, 2023). "More recently, an increase in GATA2 expression and transcriptional activity was found to confer drug resistance to leukemia and prostate cancer cells." (PMID 35289315, 2022). "One example is that the reallocation of a GATA2 enhancer element to the ectopic EVI1 site caused by translocations and inversions leads to concomitant EVI1 and GATA2 deregulation in leukemia." (PMID 34616687, 2021).
leukemia (continued). "Methods/Results: Using mice with a GATA2 haploinsufficient hematopoietic system, we generated a mouse model which developed leukemias spontaneously." (PMID 34633564, 2021). "We here show that combined biallelic Cebpa and Gata2 zinc finger-1 (ZnF1) mutations cooperatively induce bilineage AEL, and that the major leukemia-initiating cell (LIC) population has a neutrophil-monocyte progenitor (NMP) phenotype." (PMID 32330454, 2020). "In summary, we here identify combined Cebpa and Gata2 mutations as causative of bilineage AEL, providing a validated pre-clinical model for this leukemia subtype." (PMID 32330454, 2020). "We here show that, together, Cebpa and Gata2 mutations can cause bilineage AEL in mice, and that the resulting leukemia is cellularly and molecularly analogous to human AEL." (PMID 32330454, 2020). "Many of the predicted transcription factors have a known role in hematopoiesis and leukemia development (Ikzf2, Pbx3, and Hoxa13 for upregulated genes and Fos, Nkx2-2, Gata2 for downregulated genes)." (PMID 31186416, 2019). "The down-regulation of GATA2 expression was shown to be a decisive step in the progression of leukaemia by transcriptional analysis in mouse models." (PMID 31409822, 2019). "Both are GABAergic and can be distinguished based on the combinatorial expression of highly specific TFs: Forkhead Box A2 (Foxa2), GATA-binding factor 2/3 (Gata2/3), and Stem cell leukemia/T-cell acute leukemia 1 (Scl/Tal1)." (PMID 31641138, 2019). "Several proximal super-enhancers were found to be located at leukemia-associated genes such as GATA2, STAT5A/B, and ZEB2, as expected of super-enhancers found in a leukemia cell line." (PMID 28526829, 2017). "In the current study, we found that human leukemia cells that resistant to traditional chemotherapy demonstrated upregulated GATA2." (PMID 28114350, 2017). "Mutations in several other germ line leukemia predisposition genes (CEBPA, GATA2, ETV6) were also rare or undetected." (PMID 29326930, 2017). "Super-enhancer regulating leukemia associated genes such as STAT5A and GATA2 also showed enrichment of STAT5A and GATA2, respectively." (PMID 28526829, 2017). "This enhancer also has interactions with the promoter of GALNT5 and appears to be bound by a number of factors in K562 including GATA2, PML, TAL1 and BCL3, all of which have been implicated in the leukemia or other forms of cancer." (PMID 26576536, 2015). "Gata2 was recently reported for the first time as a common integration site in leukaemias induced by the MOL4070LTR retrovirus in the NHD13 mouse." (PMID 20102610, 2010). "The analysis of a larger sample of Graffi-induced megakaryoblastic leukaemias would be required to prove more efficiently the involvement of Gata2 and Kit in this particular type of leukaemia." (PMID 20102610, 2010). "Notably, several essential genes involved in HSC self-renewal, metabolism, and leukemia development were increased, including GATA2, MSI2, MYCN, CD44, GAS2, HOXB4, and HOXB6." (PMID 38216972, 2024). "Thus, some Gata2 activity appears to be required early in leukemia initiation, to open key regions in chromatin." (PMID 38648485, 2024). "In addition to the classical cBMF, several germline defects predisposing individuals to MF and potentially evolving to myelodysplastic syndrome (MDS) and leukemia have been increasingly discovered (GATA2, SAMD9, and DADA2) in the last few years." (PMID 38396760, 2024). "Furthermore, Gata2 V2 levels were decreased, and Gata2 V2 promoter DNA methylation was increased upon Cebpa depletion in an MLL-AF9 leukemic setting where CEBPA is dispensable for maintenance of the leukemia." (PMID 37794021, 2023).